POT1 (protection of telomeres 1)
Diseases named in the same sentence as POT1 in open-access papers (continued):
Sharing a sentence is not in itself a finding about the gene and the disease.
glioma (29 papers, 2014 to 2026). A benign or malignant brain and spinal cord tumor that arises from glial cells (astrocytes, oligodendrocytes, ependymal cells). "This is the first reported case of a young adult carrying a new pathogenic POT1 variant who developed a pediatric high-grade glioma and a renal tumor in early adulthood." (PMID 42232556, 2026). "Key SNPs contributing to risk of childhood glioma included rs59294613 (POT1), rs8105767 (ZNF208), and rs7705526 (TERT), which differed from the top variants previously identified in adult glioma using the same genetic instruments." (PMID 41668119, 2026). "Constitutional variants in POT1 were identified in two families with more than one individual with glioma (1% (3/301))." (PMID 40350252, 2025). "POT1 germline variants have also been identified in familial glioma, including p.G65C, which occurs at the same amino acid residue as the one reported in this study but has not been functionally validated to date." (PMID 39247651, 2024). "Exome sequencing of glioma patients from families with multiple affected members has identified rare inherited mutations in POT1 as high-penetrance glioma risk factors." (PMID 38240992, 2024). "Thirteen variants were established as germline, and for four patients, a history of cancers, allegedly associated with POT1 variants, is reported (cutaneous melanoma, glioma, thyroid cancer)." (PMID 38254993, 2024). "On the sidelines, another study suggested a correlation between glioma risk and POT1, albeit as a risk factor locus, along with others involved in telomere regulation." (PMID 38254993, 2024). "This likely pathogenic POT1 loss-of-function variant has only been reported once before as a germline variant in a patient with glioma and likely represents one of the most deleterious germline POT1 variants ever linked to familial cancer." (PMID 35456397, 2022). "While somatic POT1 mutations are most prevalent in angiosarcoma, monoallelic POT1 germline mutations are associated with a wide range of cancers, including familial melanoma, chronic lymphocytic leukemia, angiosarcoma and glioma." (PMID 34769003, 2021). "Using this approach, pathogenic germline variants in the POT1 gene encoding a member of the telomere shelterin complex were identified as predisposing to glioma, in particular to oligodendroglioma." (PMID 33929593, 2021). "For example, two POT1 germline mutations (p.Gly95Cys and p.Glu450*) were identified among one cohort of familial glioma cases (3.6%, n = 2/55), and an additional germline variant (p.Asp617Glufs) was discovered in another cohort (0.4%, n = 1/246)." (PMID 32987645, 2020). "Germline variants in POT1 have been described in familial melanoma, glioma, Li-Fraumeni-like syndrome, colorectal cancer, chronic lymphocytic leukemia, and Hodgkin lymphoma." (PMID 32492864, 2020). "Data reporting an association of constitutional variants in POT1 with familial glioma are limited." (PMID 40350252, 2025). "Furthermore, a POT1 variant (p.G65C) which occurs at the same amino acid residue as the one reported in this study, has been identified in familial glioma and is also predicted to disrupt telomere binding." (PMID 39247651, 2024). "Interestingly, a study on a native mouse glioma model demonstrated that only p.G95C, a missense variant in the POT1 OB1 DNA-binding domain, can play a proliferative role in glioma initiation." (PMID 38254993, 2024). "Mutation of human POT1 causes telomere elongation and is associated with cancers such as glioma." (PMID 36583365, 2023). "Indeed, mutations affecting the interaction domains of POT1 with ssDNA or TPP1 are associated with multiple types of human malignancies such as glioma, familial melanoma, mantle cell lymphoma, chronic lymphocytic leukemia and cardiac angiosarcoma." (PMID 35409143, 2022).
glioma (continued). "In a subsequent study, the germline and somatic molecular profiles of cancer samples were generated from 20 unrelated familial glioma patients, and these same POT1 inherited variants were identified in two cases (10%, n = 2/20), in addition to an acquired POT1 mutation at p.Arg117His (5%, n = 1/20)." (PMID 32987645, 2020). "Germline POT1 mutations have been associated with glioma, a malignant brain tumor of glial tissue." (PMID 32987645, 2020). "The individual III.9 was diagnosed with low grade glioma (at age 50) after brain MRI, prescribed as part of the screening program for POT1 carriers." (PMID 38839987, 2024). "POT1-TPD is associated with an increased lifetime risk of multiple melanomas, chronic lymphocytic leukemia (CLL), angiosarcoma, and glioma." (PMID 39156708, 2024). "It should be suspected in people with multiple CM, one of POT1-TPD core cancers (CM, CLL, angiosarcoma or glioma) and a first- or second-degree relative with a confirmed POT1-PTD cancer, or a somatic POT1 PV identified on tumour tissue sequencing." (PMID 38839987, 2024). "POT1 tumour predisposition syndrome (POT1-TPD) is inherited in an autosomal dominant manner and associated with an increased lifetime risk of cutaneous melanoma (CM), chronic lymphocytic leukaemia (CLL), angiosarcoma (mostly cardiac angiosarcomas) and gliomas." (PMID 38839987, 2024). "Furthermore, germline POT1 mutations have been shown to underlie a number of hereditary familial cancer syndromes involving CLL, glioma, melanoma and colorectal cancer and angiosarcoma." (PMID 35409143, 2022). "By analyzing glioma families, rare highly penetrant germline variants associated mainly with a predisposition for ODs were described in the POT1 gene, although not detected in this study." (PMID 33929593, 2021). "In this scenario, the less sensitive C6 cells to BRACO-19 treatment may exhibit higher levels of POT1 protein at telomeres than other glioma cells." (PMID 26908447, 2016). "No rare deleterious variants in the POT1 gene were detected in the 15 glioma families." (PMID 33929593, 2021). "The ∼10-fold difference in RHPS4 sensitivity between PFSK-1/DAOY embryonal cells and C6/GB-1 glioma cells is plausibly due to competitive binding of RHPS4 and POT1 to the 3′ overhang." (PMID 24454961, 2014).
familial melanoma (25 papers, 2015 to 2025). Familial melanoma (FM) is a rare inherited form of melanoma characterized by development of histologically confirmed melanoma in two first degrees relatives or more relatives in an affected family. "POT1 variants have been identified in familial melanoma as well as a number of other germline and somatic malignancies." (PMID 39247651, 2024). "We also observed four PTVs associated with telomere length in POT1, which is associated with familial glioma, familial melanoma, cardiac angiosarcoma and chronic lymphocytic leukemia." (PMID 39192095, 2024). "POT1 variants have been identified in familial melanoma (FM) as well as a number of other germline and somatic malignancies." (PMID 39247651, 2024). "Three percent of malignancies have POT1 mutations; however, its prevalence is higher in AS (23%) and is described among the top predisposition genes for familial melanoma and cardiac AS." (PMID 34638300, 2021). "Based on the data presented here, the inclusion of POT1 in gene panels used for investigating cancer predisposition appears to be justified for familial melanoma, angiosarcoma, cardiac sarcoma, and CLL." (PMID 32987645, 2020). "Robles-Espinoza and co-worker identified p.Y89C, p.Q94E and p.R273L mutations in the POT1 gene associated with familial melanoma." (PMID 32033110, 2020). "There are also some reports of WGS being successfully used to implicate rare, high-penetrance germline variants in cancer, for example POT1 mutations in familial melanoma and POLE and POLD1 mutations in colorectal adenomas and carcinomas." (PMID 31614935, 2019). "POT1 has been recently identified as a major susceptibility gene for familial melanoma, and is somatically inactivated in chronic lymphocytic leukemia." (PMID 26168240, 2015). "This study provides important functional validation of a novel POT1 variant in familial melanoma." (PMID 39247651, 2024). "POT1 has been reported as among the top five predisposition genes in familial melanoma." (PMID 32987645, 2020). "Finally, mutations in POT1 gene are associated with familial melanoma, glioma, chronic lymphocytic leukemia, mantle cell lymphoma, and cardiac angiosarcoma." (PMID 33322357, 2020). "There are several reports of WGS being successfully implemented to implicate rare, high-penetrance germline variants in cancer, for example POT1 mutations in familial melanoma and Hodgkin lymphoma and POLE and POLD1 mutations in colorectal adenomas or carcinomas." (PMID 32211398, 2020). "More recently, the focus has centered on germline variants in genes implicated in telomere dysregulation, including POT1, TERT, ACD, and TERF2IP, as a novel pathway underlying familial melanoma." (PMID 40851494, 2025). "Exonic POT1 mutations were also found in Austrian familial melanoma cases (1.5%, n = 2/133), but not in an Italian cohort of familial and sporadic multiple primary melanoma (MPM) cases." (PMID 32987645, 2020). "However, further studies are required to assemble comprehensive information on the frequency and the role of POT1 in familial melanoma." (PMID 29523635, 2018). "While PVs have also been detected in several other genes, including CDK4, BAP1, ATM, MITF and multiple telomere stability genes TERT, POT1, ACD, and TERF21P, about half of the cases of familial melanoma remain unexplained." (PMID 40072281, 2025). "POT1 mutations are not confined to the OB-fold domain only, instead it spread through entire length of POT1, and likely causative of many disease including CLL, familial melanoma, CMM, CP, cardiac angiosarcoma, and familial glioma." (PMID 32033110, 2020).
chronic lymphocytic leukemia (21 papers, 2015 to 2025). "Somatic POT1 variants have been identified in lymphoid neoplasms, such as chronic lymphocytic leukemia and NK/T cell lymphoma." (PMID 40202536, 2025). "In humans, germline mutations in POT1 have been identified in familial cases of melanoma, glioma, colorectal cancer, angiosarcoma, Hodgkin lymphoma and chronic lymphocytic leukemia (CLL)." (PMID 36016811, 2022). "Interestingly, an identical somatic POT1 variant has been identified in chronic lymphocytic leukemia, which further highlights its likely driver mutation status." (PMID 39247651, 2024). "POT1 has a nearly significant mutation profile in Chronic lymphocytic leukaemia." (PMID 39578854, 2024). "POT1 is frequently mutated in aggressive forms of chronic lymphocytic leukemia." (PMID 35409143, 2022). "POT1 is also frequently mutated in chronic lymphocytic leukemia." (PMID 36387164, 2022). "Germline and somatic POT1 mutations and the dysregulation of POT1 expression have been detected across different cancer types, most prevalently in cutaneous melanoma and squamous cell carcinoma, angiosarcoma, non-small-cell carcinoma of the lung and chronic lymphocytic leukemia (CLL)." (PMID 32987645, 2020). "Furthermore, our finding of telomere uncapping with POT1 deficiency is consistent with POT1 mutations identified in a subset of patients with chronic lymphocytic leukemia (CLL), which were associated with increased levels of chromosomal fusions involving telomeres." (PMID 26636039, 2015). "Differential expression patterns of telomeric proteins have been implicated in the pathogenesis of B cell-chronic lymphocytic leukemia (CLL) where the expression of TRF1 and POT1 were reduced more than two-fold whereas ACD and RAP1 showed increased expression." (PMID 32674474, 2020). "The highest prevalence of POT1 alterations has been observed in cutaneous melanoma, non-small-cell lung carcinoma, squamous cell carcinoma, chronic lymphocytic leukemia, and AS." (PMID 40666093, 2025).
angiosarcoma (15 papers, 2019 to 2025). A malignant tumor arising from the endothelial cells of the blood vessels. "POT1, a gene involved in regulating telomere length, has been shown to be mutated in head and neck angiosarcoma three times more frequently than in other angiosarcomas." (PMID 41301029, 2025). "Within angiosarcoma, all the POT1 alterations were short variant alterations, occurring throughout its length, where 70% of the mutations were observed only once and none were observed more than twice." (PMID 37709802, 2023). "Further study by the same group has uncovered a wide spectrum of POT1 variants in patients with familial angiosarcoma, as well as sporadic angiosarcoma and sarcomas." (PMID 36387164, 2022). "The highest frequency of POT1 mutation was found in pulmonary sarcomatoid carcinomas (28%) and angiosarcomas (23%), which are particularly aggressive malignancies compared with other types of sarcomas in which the frequency of POT1 mutations was not elevated." (PMID 35727838, 2022). "Subsequent characterization of the spectrum of POT1 mutations in 62,368 solid tumors has revealed a strong association between the presence of POT1 mutations and angiosarcoma development." (PMID 36387164, 2022). "It is of particular relevance that POT1 mutations are mainly associated to increased angiosarcomas both in mice and humans." (PMID 35727838, 2022). "Among the tumor categories with more than 50 cases, angiosarcoma (23.3%, n = 20/86) and cutaneous squamous cell carcinoma (9.1%, n = 20/220) had the highest prevalence of POT1 mutations." (PMID 32987645, 2020). "POT1 constitutional variants, and in particular missense variants that are located within functional domains and are considered damaging by functional predictors, have been identified in individuals with angiosarcoma, mainly cardiac (CAS) and breast." (PMID 40350252, 2025). "We cannot comment on whether these POT1 mutations in our study were associated with head and neck angiosarcomas due to data limitations." (PMID 41301029, 2025). "Cardiac angiosarcomas, though rare, have also been associated with POT1 mutations." (PMID 41301029, 2025). "Thus, pathological POT1 mutant variants seem to be associated to the increased aggressiveness of pulmonary sarcomatoid carcinomas and angiosarcomas." (PMID 35727838, 2022). "Overall, the alteration prevalence for these genes was low, where GID4 was altered in 3.6% (83/2332) of soft tissue sarcoma nos, POT1 in 6.3% (38/606) of angiosarcoma, and RAD51B in 3.6% (38/1055) of uterus leiomyosarcoma samples." (PMID 37709802, 2023). "We also observed a trend towards higher median TERRA levels in POT1 altered angiosarcoma vs WT (12.5 vs 5.8, p > 0.05) and a trend towards higher levels in RAD51B altered uterus leiomyosarcoma vs WT (46.7 vs 30.1, p > 0.05)." (PMID 37709802, 2023). "Screening for POT1 and other LFS/LFL or angiosarcoma causative genes might be of great clinical relevance." (PMID 36387164, 2022). "POT1 variants were subsequently observed in 10% of sporadic CAS (n = 1/10), and 10% of sporadic cardiac sarcoma (n = 2/20), while 20% of LFL families with members who suffered from angiosarcoma had a POT1 germline mutation (n = 2/10)." (PMID 32987645, 2020). "As referred before, there is growing evidence suggesting that POT1 PV could increase the risk of sarcoma and not just angiosarcoma." (PMID 38839987, 2024). "Of note, no POT1 variant was found in 24 LFL families without angiosarcoma cases." (PMID 38254993, 2024).
thyroid cancer (15 papers, 2019 to 2025). "In the same year, a study proposed an association between the SNP rs58722976, corresponding to a POT1 intronic variant, and found in three out of 110 childhood cancer patients, and the risk for subsequent thyroid malignant neoplasm." (PMID 38254993, 2024). "Mutations in POT1 were first reported in familial melanoma, where some family members also developed thyroid cancer." (PMID 38571492, 2024). "used functional variant approaches to confirm the association between low-frequency intronic regulatory POT1 variants in survivors of childhood cancer and subsequent development of malignant thyroid tumors." (PMID 38571492, 2024). "In the family #3, the index had had thyroid cancer preceding MM and carried P variants in POT1, CHEK2, and MUTYH but the father with MM (#3_I.1) shared only the CHEK2 and MUTYH variants." (PMID 36467798, 2022). "Although a number of studies show telomere shortening to be associated with cancers of the thyroid, mutations in POT1 are predicted to cause telomere lengthening and increase susceptibility to various cancers." (PMID 32492864, 2020). "Genotype frequencies and Cox regression estimates for POT1 rs58722976 and risk of subsequent malignant neoplasm of the thyroid in the Childhood Cancer Survivor Study." (PMID 32040538, 2020). "In our study, we identified a novel germline POT1 missense mutation that segregated with thyroid cancer in an Italian family." (PMID 32492864, 2020). "In survivors of childhood cancer, the presence of the POT1 rs58722976 variant has been linked with an increased risk of developing a subsequent thyroid cancer." (PMID 32987645, 2020). "The association between POT1 and thyroid cancer remains provisional and justifies further research." (PMID 38540414, 2024). "Moreover, an association between the increased risk of thyroid cancer and the presence of an intronic variant of POT1 (rs58722976) was also observed in a cohort of childhood cancer survivors." (PMID 33218058, 2020). "Finally, a highly penetrant POT1 mutation (p.Lys90Glu) was recently discovered in a large US family, where carriers suffered from a range of different cancer types including multiple primary melanoma, thyroid cancer, breast cancer and others." (PMID 32987645, 2020). "The POT1 p.P35L variant was detected in all of the affected individuals with cancers, including those with NSCLC, sarcoma, thyroid cancers, as well as the individual with childhood-onset cardiac angiosarcoma (III8)." (PMID 36387164, 2022). "Furthermore, three of them had also been diagnosed with another POT1‐related malignancy: AML, MPN, osteosarcoma, and two cases of thyroid cancer." (PMID 36467798, 2022).